RPS19 (ribosomal protein S19)
Diseases named in the same sentence as RPS19 in open-access papers (continued):
Sharing a sentence is not in itself a finding about the gene and the disease.
breast carcinoma (9 papers, 2018 to 2024). "Decreasing RPS19 in tumor cells or interrupting the C5AR1-RPS19 interaction reduces RPS19-mediated immunosuppression, impairs tumor growth, and delays the development of tumors in an in vivo assay of breast cancer." (PMID 38729966, 2024). "In these models, Rps19/C5aR1 signaling is selectively elevated in TAM_C3, which predominantly expresses genes associated with an anti-inflammatory/protumor state.However, whether C5a/C5aR pathway are involved in ferroptosis during breast cancer carcinogenesis remains unclear." (PMID 39483473, 2024). "Maciej M. Markiewski demonstrated that ribosomal protein S19 interacts with C5aR1 and promotes breast cancer growth by facilitating the recruitment of MDSCs to tumors." (PMID 39483473, 2024). "Blocking C5AR1-RPS19 interaction decreases RPS19-mediated immunosuppression and impairs tumor growth in a breast cancer model." (PMID 38002057, 2023). "RPS19, one of the DEGs in metastatic breast cancer cells, is an immunosuppressive molecule expressed by metastatic breast cancer cells, and its interaction with C5AR1 of macrophages was also identified in the metastases of five lymph nodes." (PMID 36148946, 2022). "When the expression level of RPS19 is decreased, the tumor growth is impaired, and the development of tumors is also delayed in a transgenic model of breast cancer." (PMID 33133154, 2020). "In particular, ribosomal protein S19 (RPS19), which is known to be up-regulated in human ovarian and breast cancer cells and released from apoptotic tumor cells, was found to be associated with a novel immunosuppressive property." (PMID 30255801, 2018). "For example, RPS19, RPS21, and RPS24 can be used as biomarkers for prostate cancer, and ribosome dysfunction is associated with the pathogenesis of nasopharyngeal carcinoma and can promote breast cancer metastasis." (PMID 34796111, 2021). "This suggests that the immunomodulatory effects of atovaquone in breast cancer could also be due to a reduction in the expression of RPS19." (PMID 34068008, 2021). "Moreover, downregulation of RPS19 or RPL39 suppressed breast tumor growth and progression in a transgenic breast cancer model, or tumor initiation and lung metastasis in patient-derived and human breast cancer xenografts, respectively." (PMID 30425236, 2018).
colon carcinoma (6 papers, 2016 to 2024). "The earliest reported relationship between RPs and cancer was published in the 1990s, which demonstrated the association of eS19 (RPS19) expression levels with colon carcinoma progression and differentiation." (PMID 38989007, 2024). "In mice, RPS19 plays a critical role during early developmental stages and is highly expressed in certain colon cancer types." (PMID 39858295, 2024). "Daptomycin has also been reported to selectively inhibit the growth of breast and colon cancer cells in vitro by binding to the human ribosomal protein S19 (RPS19) within the 40S ribosomal subunit." (PMID 39858295, 2024). "A high level of RPS19 and laminin-binding protein (LBP) mRNAs, combined with low level of HLA-I, are linked to high malignancy of colon carcinoma." (PMID 34873618, 2021). "Immunosuppressive properties were proposed for RPS19, also increased in colon cancer cells and released from apoptotic tumor cells." (PMID 31506518, 2019). "Similarly, the mRNA of RPS19 has been shown to be overexpressed in primary colon carcinoma tissues and present in both well and poorly differentiated cell lines." (PMID 34873618, 2021). "With higher expression levels of RPS19 in certain colon cancer cells, RPS19 may be a promising drug target protein for DAP anticancer activity." (PMID 31263709, 2019).
ovarian carcinoma (6 papers, 2018 to 2022). A malignant neoplasm originating from the surface ovarian epithelium. "RPS19 is upregulated in breast and ovarian cancer cells and promotes the presence of regulatory T cells, reducing CD8 T cell infiltration." (PMID 34326696, 2021). "Ovarian cancer cells overexpress ribosomal protein S19 (RPS19), which leads to tumor growth through its interaction with C5aR1 in MDSCs." (PMID 34359708, 2021). "RPS19 was reported to be overexpressed in breast and ovarian cancer, and its interaction with C5AR1 could induce the secretion of immunosuppressive cytokines and promote the generation of Treg cells." (PMID 34611125, 2021). "Examination of the resulting network shows that RPS19, PNOC, SFRP1 and KCNJ16 are connected to other frequently altered genes, including MYC or EIF3E as oncogenes, from TCGA ovarian cancer dataset." (PMID 30255801, 2018). "Although this interaction has never been described in the context of glioma, the ribosomal protein S19 (RPS19) is upregulated in breast and ovarian cancers, and its interaction with the C5a receptor 1 (C5AR1), expressed on tumor-infiltrating myeloid cells, has an immunosuppressive effect." (PMID 33155039, 2020).
prostate carcinoma (6 papers, 2016 to 2021). A carcinoma that arises from epithelial cells of the prostate gland. "In addition to an increased level of pAMPK, which has been previously reported in a prostate carcinoma cell line transfected with RPS19-specific small interfering RNAs31, we observed an increase in MDM2 expression." (PMID 28931864, 2017). "The top 10 genes upregulated in TRAMP mice are TNFSF, RPL22, EIF4, SLC2A, LMO2/3, KRT, RPS21, RPS19, RPL21, and NEK of which all 10 were upregulated in human prostate cancer dataset." (PMID 30972102, 2019). "These included: the erythroleukemia cell lines K562C and TF-1C inducible for the expression of siRNA against RPS19 mRNA; the prostate cancer cell line 22Rv1 and the embryonic kidney cell line HEK293 both transiently transfected with siRNA for RPS19." (PMID 27734913, 2016). "Our results show that RPS19, RPS21 or RPS24 are upregulated in malignant tissue and may serve as putative biomarkers for prostate cancer." (PMID 29016636, 2017).
bone marrow failure syndrome (5 papers, 2018 to 2023). "Many of the differentially downregulated ribosomal genes (e.g. RPS19, RPS28) have been causally associated with human bone marrow failure syndromes and hematologic malignancies." (PMID 29954325, 2018). "In 1999, recurrent mutations in the ribosomal protein gene RPS19 (also known as eS19) were reported in patients with Diamond–Blackfan anemia (DBA), a congenital bone marrow failure syndrome." (PMID 30862070, 2019).
erythroblastopenia (5 papers, 2012 to 2023). "For example, mutations to RPS19 are associated with a congenital erythroblastopenia with a decreased abundance or lack of erythroid precursors." (PMID 28253842, 2017).
bone marrow failure (4 papers, 2018 to 2024). "Our findings define a robust and scalable experimental model for RPS19-mutated DBA, and provide potential insights into mechanisms of bone marrow failure that occurs in older affected patients." (PMID 36413407, 2023).
cervical cancer (4 papers, 2012 to 2026). A primary or metastatic malignant neoplasm involving the cervix. "In one previous study, RPS19 has also been shown to be associated with the risk of cervical cancer and persistence of HPV." (PMID 23826176, 2013). "The RPS19 rs2305809 T allele was also associated with statistically significant decreased risk of cervical cancer (ORCT=0.66, 95%CI 0.48–0.91; ORTT=0.43, 95%CI 0.28–0.66, Ptrend=0.00007)." (PMID 22496757, 2012).
colorectal cancer (4 papers, 2013 to 2025). A primary or metastatic malignant neoplasm that affects the colon or rectum. "Previous studies have shown that overexpression of rps19 mRNA is correlated with malignant potential in colorectal cancer (CRC) cell lines." (PMID 29016636, 2017).
leukemia (4 papers, 2004 to 2025). A malignant (clonal) hematologic disorder, involving hematopoietic stem cells and characterized by the presence of primitive or atypical myeloid or lymphoid cells in the bone marrow and the blood. "Although RpS19 heterozygosity disrupts ribosome biogenesis 22–24, how reduced levels of Rps promote the excessive proliferation associated with progression to leukemia remains unclear and whether the mechanism is related to tissue overgrowth of Minutes has not been investigated." (PMID 22194697, 2011). "Genetic disruption of Wnk1 strongly suppressed the growth of MA9 leukaemia cells to a degree comparable to targeting the essential gene Rps19." (PMID 40425534, 2025). "For example, mutations in RpS19, RpS17, RpS24, RpL35a, RpS7, RpL5, RpL11, RpS10 and RpS26 have been associated with the human disease Diamond Blackfan Anemia (DBA), a dominant autosomal bone marrow failure syndrome, characterised by hypoplastic anemia with a predisposition to leukemia." (PMID 22194697, 2011).
red cell aplasia (4 papers, 2009 to 2020). "It has been suggested that non-coding RPS19 sequence variants contribute to the considerable clinical variability in red cell aplasia." (PMID 19587786, 2009).
Shwachman-Diamond syndrome (3 papers, 2013 to 2023). "We also observe an increase of autophagy in cells derived from DBA patients, in CD34+ erythrocyte progenitor cells with RPS19 knock down, in the red blood cells of zebrafish embryos with RP-deficiency, and in cells from patients with Shwachman-Diamond syndrome (SDS)." (PMID 24875531, 2014).
osteosarcoma (2 papers, 2011 to 2020). A usually aggressive malignant bone-forming mesenchymal neoplasm, predominantly affecting adolescents and young adults. "Next, we compared thetranscriptional stability of several normalizers that were formerly recommendedfor use in canine osteosarcoma without transcriptome-wide expression profiling forthis context such as OAZ1 or B2M,HNRNPH, RPS5 and RPS19." (PMID 32296879, 2020).
rheumatoid arthritis (2 papers, 2021). A chronic, systemic autoimmune disorder characterized by inflammation in the synovial membranes and articular surfaces. "A monocyte-specific chemoattractant ribosomal protein S19 (RP S19) polymer in rheumatoid arthritis synovial tissues was demonstrated as an alternative ligand of C5a receptor (C5aR), which belongs to the chemotactic G protein-coupled receptor (GPCR) family." (PMID 33490647, 2021). "Dimerised ribosomal protein S19 (RP S19) is a find-me signal for monocytes, first discovered in the context of rheumatoid arthritis." (PMID 34177884, 2021).
acute kidney injury (1 paper, 2022). Sudden and sustained deterioration of the kidney function characterized by decreased glomerular filtration rate, increased serum creatinine or oliguria. "A few years later, they further confirmed the protective effects of RPS19 treatment in a mouse model of cisplatin-induced acute kidney injury, showing downregulation of MIF/CD74-induced inflammation, which was similar to results found with MIF knock-out mice." (PMID 35091838, 2022).
Bradycardia (1 paper, 2023). A slower than normal heart rate (in adults, slower than 60 beats per minute). "We present the unusual case of a six month old infant with a de novo mutation of the RPS19 gene causing Diamond–Blackfan anemia who additionally suffers from severe sinus bradycardia." (PMID 36837563, 2023).
breast tumor (1 paper, 2021). "Reducing RPS19 in tumor cells or blocking the interaction between MDSCs’s C5a receptor and RPS19 decreases RPS19-mediated immunosuppression, which leads to impairment in breast tumor growth." (PMID 34068008, 2021).
depression (1 paper, 2024). "In particular, ribosomal protein S19, ribosomal protein S12, ribosomal protein S14, vimentin, and ubiquitin-like modifier activating enzyme 1 mediated the therapeutic effects of EXD on depression and hippocampal damage." (PMID 38915473, 2024).
gastric cancer (1 paper, 2022). A primary or metastatic malignant neoplasm involving the stomach. "We performed a drug-target prediction analysis using the Genomics of Drug Sensitivity in Cancer (GDSC) database and identified candidate drugs (ZG10, Dasatinib, CGP-082996) for HS6ST2, RPS19, and SERPINE1 in gastric cancer." (PMID 35954218, 2022).
glioblastoma (1 paper, 2022). The most malignant astrocytic tumor (WHO grade IV). "Eight genes associated with glioblastoma prognosis were identified based on LASSO analysis: RPS10, RPS11, RPS19, RSL24D1, RPL39L, EIF3E, NUDT5, and RPF1." (PMID 36733371, 2022). "Eight genes—RPS10, RPS11, RPS19, RSL24D1, RPL39L, EIF3E, NUDT5, and RPF—were found to have an expression in the prognosis of glioblastoma." (PMID 36733371, 2022).
glioma (1 paper, 2020). A benign or malignant brain and spinal cord tumor that arises from glial cells (astrocytes, oligodendrocytes, ependymal cells). "Among the top-scored L–R autoc-rine pairs, there was an interaction between RPS19 and C5AR1, detected in all the patients with glioma tested (n = 39, P = 6.68 · 10−76)." (PMID 33155039, 2020).
Myocardial fibrosis (1 paper, 2022). "Our previous study demonstrated the involvement of ribosomal protein S19 (RP S19)-mediated transforming growth factor β1 (TGF-β1) signaling in I/R-induced myocardial fibrosis." (PMID 35910357, 2022).
neuroblastoma (1 paper, 2020). Neuroblastoma (NB) is the most common solid, extracranial childhood tumor. "Most genes in ribosome signaling pathway were up-regulated in MYCN amplified neuroblastoma patients, as demonstrated the RPS19 expression levels in TARGET, GSE19274, GSE49710, GSE73517 and GSE85047 datasets." (PMID 32593299, 2020). "Only, RPS19 demonstrated poor prognostic effects in patients with neuroblastoma in TARGET and GSE85047 datasets." (PMID 32593299, 2020). "Furthermore, RPS19 in ribosome signaling pathway was also associated with MYCN amplification and correlated with the poor prognosis of neuroblastoma." (PMID 32593299, 2020).
renal fibrosis (1 paper, 2025). A final common manifestation of a wide variety of chronic kidney diseases characterized by glomerulosclerosis and tubulointerstitial fibrosis. "The expression levels of Rps19, Isg20, and Rps9 were significantly upregulated in renal fibrosis samples from both the GSE42303 and GSE121190 datasets." (PMID 40622935, 2025). "Further analysis yielded three ribosome biogenesis-related DEGs, including Rps19, Rps9, and Isg20, which were significantly upregulated in renal fibrosis samples." (PMID 40622935, 2025). "Among these, Rps19, Rps9, and Isg20 were significantly upregulated in UUO-induced renal fibrosis mouse kidney samples, with Isg20 showing the highest level of upregulation." (PMID 40622935, 2025).
squamous carcinoma (1 paper, 2020). "A recent study using human squamous carcinoma cell lines has shown that luteolin ameliorates cancer metastasis by reducing the expression and activity of ribosomal protein S19 and inhibiting the AKT/mTOR/c-Myc signaling pathway." (PMID 32224968, 2020).
Tinnitus (1 paper, 2024). Tinnitus is an auditory perception that can be described as the experience of sound, in the ear or in the head, in the absence of external acoustic stimulation. "The most downregulated genes in the tinnitus (when compared to the non-tinnitus group) were LOC103690064, AABR07048397.1, Trpv1, AABR07061378.1, Ncaph, Spata20, Rps19, Enpp3, Grtp1, and Glra1." (PMID 38562529, 2024).
triple-negative breast carcinoma (1 paper, 2021). An invasive breast carcinoma which is negative for expression of estrogen receptor (ER), progesterone receptor (PR), and human epidermal growth factor receptor 2 (HER2). "RPS19 induces the production of immunosuppressive cytokines and promotes tumor growth which can be impaired by the blockage of RPS19 while the knockdown of RPL39 in triple-negative breast cancer (TNBC) xenografts reduces significantly primary tumor growth, as well as metastasis." (PMID 34873618, 2021).
cancer (32 papers, 2004 to 2025). A tumor composed of atypical neoplastic, often pleomorphic cells that invade other tissues. "Among the most recurring ligands, we found several instances that are either invariably associated to lower survival, e.g., CXCL5, CXCL1, GAL, and RPS19, or have opposite associations depending on the cancer type, e.g., CXCL9." (PMID 38723607, 2024). "In cancer cell lines and animal models, RPS19 deficiency disrupts nucleolar ribosomal assembly, resulting in the accumulation of other RPs that diffuse into the nucleoplasm." (PMID 36413407, 2023). "Of the genes identified to be associated with CIN3/cancer RPS19 was also associated with progression to CIN3/cancer (p-value 0.006)." (PMID 22496757, 2012). "DBA variants in patients with cancer/MDS refer mainly to RPS19, RPL35A, RPL11, RPL5, RPS17, and GATA1 genes (18%, 13%, 10%, 5%, 3%, and 3%, respectively; 49% unknown)." (PMID 38002903, 2023). "Mutations in RPS19 cause an impairment of ribosome biogenesis and protein synthesis but how this leads to erythroid failure, congenital malformations and cancer is unknown." (PMID 20454576, 2010). "Cell–cell interaction analysis identified that cancer cells and macrophages in the highest stemness cluster communicate through the common ligand RPS19." (PMID 35954218, 2022). "As the components of ribosome, Rps15a, Rps19, Rpl14, Rpl22 were preciously controlled by Myc and highly expressed in cancer cells, which promoted the EMT process." (PMID 34955855, 2021). "Myeloid cell-cancer cell communication analyses revealed activation of C5AR1/RPS19 and HLA-C/FAM3C pairs." (PMID 34326696, 2021). "In another example, an alternative promotor region in the ribosomal protein S19 (RPS19) gene induced the expression of the cancer-specific 71 AA short cMDT ENST00000221975 in 100% of Panc-AdenoCA, 98% of Uterus-AdenoCA and 93% of Stomach-AdenoCA." (PMID 32879328, 2020). "It was further suggested that RPS19 immunosuppressive role in cancer involved its interaction with the complement receptor C5aR1 (CD88), promoting tumor growth in a transgenic model of breast cancer." (PMID 31506518, 2019). "In conclusion, a genome wide, unbiased reverse chemical proteomics screen of DAP binding protein(s) in several human cancer cells identified RPS19 as a biophysically and biologically relevant target protein of DAP in humans." (PMID 28680364, 2016). "The single most significant SNPs from each gene associated with CIN3/cancer were PRDX3 rs7082598 (Ptrend<0.0001), and RPS19 rs2305809 (Ptrend=0.0007), respectively." (PMID 22496757, 2012). "Regions statistically significantly associated with CIN3/cancer included genes for peroxiredoxin 3 PRDX3, and ribosomal protein S19 RPS19." (PMID 22496757, 2012). "For instance, quercetin, the key component of Huangqi, could inhibit metastasis of cancer cells by blocking Akt/mTOR/c-Myc signaling pathway to suppress RPS19-activated EMT signaling." (PMID 36313348, 2022). "Importantly, none of SNPs associated with the two genes of interest (PRDX3 and RPS19) were statistically significantly different between CIN3 and cancers." (PMID 22496757, 2012). "It is unknown whether there is any genotype-phenotype correlation between RPS19 mutations, or other DBA genes, and cancer predisposition." (PMID 18671700, 2008). "Similarly, myeloid cells communicate with cancer cells via C5AR1/RPS19." (PMID 34326696, 2021). "It was proposed that RPS19 was one of the marker of epithelial-mesenchymal transition (EMT), and regulated the metastasis abilities of cancer cells by in vitro assays." (PMID 38729966, 2024). "The most frequent cMDT disrupting interactions in over 90% of samples of a cancer type were those from the genes USP46, WDR74, RPS19, BOLA2B, NDUFA9, and LAMA3." (PMID 32879328, 2020). "Only two of the genes - PRDX3 and RPS19, were notable with a FDR≤0.2 comparing CIN3/cancers to random controls." (PMID 22496757, 2012).